TNF (tumor necrosis factor)
Diseases named in the same sentence as TNF in open-access papers (continued):
Sharing a sentence is not in itself a finding about the gene and the disease.
cardiovascular disease (continued). "The ability of pro-inflammatory mediators, such as TNFα, interleukin-1, and platelet-derived growth factor, to enhance OPG expression and production in vascular cells, may explain the association between OPG concentrations and cardiovascular diseases." (PMID 35454141, 2022). "IL-6 and TNF-α stimulate the production of C-reactive protein by the liver, and together, they trigger the subclinical inflammation process, which in turn may result in the onset of cardiovascular diseases during adolescence." (PMID 34411143, 2021). "Monitoring the trace concentration of TNF-α in these body fluids provides a painless, simple, real-time means for cardiovascular disease diagnosis; in particular, it may serve as a sign of inflammation, which is important for the early diagnosis of some acute diseases, such as acute heart failure." (PMID 34621727, 2021). "Therefore, TNF-α may be a key mediator which is linked to T2DM and cardiovascular diseases in women with PCOS." (PMID 27764100, 2016). "In addition, estrogen may also mediate a variety of chronic inflammatory diseases, including cardiovascular diseases, by inhibiting the expression of tumor necrosis factor." (PMID 26757267, 2016). "TNF-α might also play a key role in the development of cardiovascular disease." (PMID 27764100, 2016). "Thus, the downregulation of TNF-α and IL-6 is necessary in the treatment of cardiovascular disease." (PMID 25371725, 2014). "This response is characterized by increased production of proinflammatory and proatherogenic cytokines, such as interleukin-6 (IL-6) and tumor necrosis factor (TNF), both involved in the pathogenesis of cardiovascular diseases." (PMID 40001466, 2025). "This mutual upregulation of TNF‐α and CEACAM1 would establish a vicious cycle promoting inflammaging and eventually the development of cardiovascular diseases." (PMID 39434463, 2025). "Leucocytes produce proinflammatory cytokines, such as TNF-α and IFN-γ, which contribute to SMC apoptosis in cardiovascular disease." (PMID 39742015, 2024). "Aspirin reduces the expression of several inflammatory markers in cardiovascular disease (CVD), such as hs-CRP, IL-6, MCP-1, M-CSF, and TNF-α." (PMID 38836066, 2024). "TNF has been shown to modulate the expression of NADPH oxidases, which are a known potential source of ROS within cardiovascular diseases." (PMID 36671012, 2023). "Recent studies have shown that the intima of arteries with atherogenesis as cardiovascular disease (CVD) even before any clinical manifestation, accompanied by tumor necrosis factor and interleukins." (PMID 36980032, 2023). "As an essential modulator in TNF-α-induced inflammatory responses, TACE is emerging as a potential molecular target in the treatment of cardiovascular diseases." (PMID 36439267, 2022). "In addition, less favorable profiles of circulating inflammatory markers including tumor necrosis factor-α, C-reactive protein, and adiponectin in patients with GDM may also contribute to the association between a history of GDM and risk of cardiovascular diseases." (PMID 35865249, 2022). "A case–control study with a designated experimental group of 110 patients with histories of cardiovascular disease (CVD) showed that s-Klotho levels were significantly lower in the CVD group and inversely correlated with CRP and TNFα/IL10." (PMID 35603960, 2022). "VSMC proliferation and migration is promoted by TNF-α in other diseases, and by TNF-α and other transcription factors in some cardiovascular diseases." (PMID 34858201, 2021). "As expected, among the cardiovascular disease related genes, MMP9, TNF, IFN-ɣ, and VCAM1 genes were the top up-regulated genes in ILC1s was earlier shown to play an important role in the occurrence of post-PCI restenosis." (PMID 32198366, 2020).
cardiovascular disease (continued). "A close correspondence between gene expression and post-translational histone modifications is found in proinflammatory molecules, including tumor necrosis factor alpha (TNF-α) and COX2 under metabolic and cardiovascular diseases." (PMID 32748067, 2020). "During vascular inflammation, TNF-α gene transcription was time-dependently upregulated, indicating the active involvement of TNF-α in the development of cardiovascular disease." (PMID 25114952, 2014). "Of note however, healthy patients alone were able to induce significant TNF release upon PMA/ionomycin, suggesting a highly activated and exhausted iNKT phenotype in HIV-patients with cardiovascular disease." (PMID 25329381, 2014). "In the last years, different markers of inflammation (such as CRP, IL-6, and TNF-alpha, among others) have been studied in prediction of coronary events; on this regard, CRP is the most important marker for cardiovascular disease." (PMID 23690772, 2013). "Recent evidence suggests that tumor necrosis factor alpha (TNF) and angiotensin II (ANGII) induce oxidative stress contribute to cardiovascular disease progression." (PMID 23056347, 2012). "The release of these fatty acids, coupled with some inflammatory cytokines production like tumor necrosis factor-alpha (TNF-α) and interleukin-6 (IL-6), instigates systemic inflammation and the onset of metabolic disorders like cardiovascular disease and type 2 diabetes." (PMID 39774749, 2025). "It is speculated that multiple inflammatory factors such as IL-6a, IL1β, and TNF-α play a crucial role in BPH and cardiovascular diseases." (PMID 40636389, 2025). "However, it should be noted that dysregulation of the TNF, IFNG, and TGFB seems more specific for classical cardiovascular disease." (PMID 38389898, 2024). "Investigating the potential of other inflammatory markers, such as TNF-α, MCP-1, and CRP, could provide a more comprehensive understanding of the inflammatory landscape in cardiovascular diseases." (PMID 39057626, 2024). "Furthermore, recent research analyzing macrophages extracted from blood samples of patients with cardiovascular disease has revealed significant downregulation of autophagy‐related genes LC3 and Atg5, accompanied by a marked increase in TNF‐α levels." (PMID 39508636, 2024). "Cardiovascular disease (CVD) is a general term for disorders of the heart and blood vessels and is characterized by increased expression of IL-6 and tumor necrosis factor-α (TNFα)." (PMID 37434075, 2023). "It has been proposed that free mitochondria could be important mediators of cardiovascular disease by inducing activation of type I IFN and TNF signaling." (PMID 36052991, 2022). "Previous studies have confirmed that vascular endothelial inflammatory factors IL-1β, TNF-α, and adhesion factors ICAM-1 and VCAM-1 are essential markers of vascular endothelial injury and dysfunction, which can predict cardiovascular disease, and correlate with the severity of ACS." (PMID 35302437, 2022). "Moreover, the interplay between TNF-α and VCAM-1 plays an important part in cardiovascular disorders." (PMID 35281466, 2022). "Catechin also improves redox imbalance and mitochondrial dysfunction, a prominent feature of cardiovascular disease, by stimulating phosphorylation of AMPK and ACC, inhibiting the key enzymes of de novo lipogenesis, and blocking the TNF-α-induced insulin signaling pathway." (PMID 32831990, 2020). "Among uninfected ambulatory adults without cardiovascular disease, RDW was associated with elevated pro-inflammatory cytokines (TNF-α, IL8, IL6, IL1b), but not regulatory cytokines (TGFb)." (PMID 33089037, 2020). "Nevertheless, we demonstrated here that TNFα-induced EC inflammation is reduced by apoB-depleted plasma similarly to HDL isolated by ultracentrifugation, which is of interest for investigators studying cardiovascular disease." (PMID 30678190, 2019).
cardiovascular disease (continued). "Apart these aspects, social integration was related to chronic low-grade inflammation with lower levels of inflammatory cytokines include interleukin (IL)-1, tumor necrosis factor (TNF), and C-reactive protein, which appears critical in the progression of cardiovascular disorders." (PMID 31035622, 2019). "In the recent years, chemerin and TNF-α have gradually taken focus on cardiovascular disease, but there is a lack of clinical studies for the changes of above adipokines in sHT." (PMID 29686704, 2018). "IL-1β, TNF-α, and IL-6 stimulated the liver to produce high-sensitivity CRP (hs-CRP), which had a strong relationship with the recurrent events of cardiovascular diseases as shown in several randomized clinical trials." (PMID 29403392, 2018). "Adipocyte TNF-α production was higher among people with a family history of cardiovascular disease, but was not affected by GI." (PMID 27598983, 2017). "Thus, DSSM exerts effects against cardiovascular diseases by targeting JUN, TNF, NFKB1, FOS, and BCL2." (PMID 29348768, 2017). "Randomized controlled trials of aspirin conducted among patients with cardiovascular disease found statistically significant reductions in circulating concentrations of high-sensitivity C-reactive protein (CRP), tumor necrosis factor-alpha (TNF-α), interleukin-6 (IL-6), and thromboxane B2 (TXB2)." (PMID 28542447, 2017). "There is evidence from large epidemiological studies that levels of CRP, IL-6, and TNF-α are independent predictors of future cardiovascular events and mortality in subjects with and without known cardiovascular disease." (PMID 24895539, 2014). "The elevated levels of TNF-α and MCP-1 in the present study may be relevant for cardiovascular disease." (PMID 24349251, 2013). "In contrast, pro-inflammatory cytokine TNFα mediates the relationship between urinary Cys-C and ox-LDL, indicating that the renal system, possibly through inflammation, is more closely regulated by TNFα, potentially contributing to renal and cardiovascular diseases." (PMID 40243674, 2025). "However, for the subgroup of patients with baseline cardiovascular disease, point estimates indicated a lower incidence of ADRD with TNF inhibitors in 2 of 4 analyses (analysis 1: HR, 0.76 [95% CI, 0.50-1.16]; analysis 2: HR, 0.74 [95% CI, 0.56-0.99]; analysis 3: HR." (PMID 35394510, 2022). "With TNFR1 having strong apoptotic and negative inotropic effects, it has been hypothesized that TNF alpha inhibitors should have therapeutic effects in patients with cardiovascular disease." (PMID 34660128, 2021). "Secondly, this study was only designed to examine the hs‐CRP levels but not to other inflammatory biomarkers such as IL‐6 and tumor necrosis factor α, which have also been identified as stronger predictors of clinical events in patients with cardiovascular diseases." (PMID 32458487, 2020). "Therefore, TNF-α may be a useful biomarker for the diagnosis of PCOS and the treatment of T2DM and cardiovascular diseases in women with PCOS." (PMID 27764100, 2016). "Our data suggest that TNF-α and IL-6, but not CRP, are associated with the prevalence and severity of CKD, independent from established CKD risk factors, history of cardiovascular disease, and use of antihypertensive, antidiabetic, and lipid-lowering agents and aspirin." (PMID 26025192, 2015). "In metabolic and cardiovascular disease states, EAT reduces the production of cardioprotective adipocytokines, such as adiponectin, and induces the production of detrimental pro-inflammatory adipocytokines such as leptin, resistin, IL-6, tumor necrosis factor-α, and IL-17." (PMID 23409197, 2013). "Identifying the links between TNF, ANGII, and oxidative stress at the mitochondrial level in contributing to cardiac damage may lead to a better understanding of the progression of cardiovascular disease and, ultimately, lead to new and effective treatment strategies." (PMID 23056347, 2012).
cardiovascular disease (continued). "We did not evaluate high-sensitivity CRP, IL-1, IL-6, ST2, TNFα, or VEGF, all of which are considered inflammatory regulators in cardiovascular diseases." (PMID 35328412, 2022). "This review summarizes the effects of anti-TNF-α treatment in patients with and without heart disease and describes the involvement of TNF-α signaling in a number of animal models of cardiovascular diseases." (PMID 33053859, 2020). "Series of anti-RA drugs used in the clinic, such as methotrexate, inhibitors of Janus kinase (JAK), and tumor necrosis factor (TNF), would induce nonnegligible side-effects such as cytopenia, transaminase elevation, cardiovascular disease (CV), and gastrointestinal (GI) events." (PMID 34393779, 2021). "The combination of elevated CRP and TNF-α in these non-obese young women coalesces sufficiently that PCOS may link to the development of T2DM and cardiovascular disorder." (PMID 23825680, 2013). "A possible explanation for our findings is that neutrophilic airway inflammation is associated with some systemic inflammation pathways, such as TNFα which is known to be involved in muscle inflammation, but not CRP which is an indicator of cardiovascular disease." (PMID 19480658, 2009).
neurodegenerative disease (445 papers, 2005 to 2026). A disorder of the central nervous system characterized by gradual and progressive loss of neural tissue and neurologic function. "The plasma levels of pro-inflammatory cytokines (IL-6, TNF and IL-1β) are accepted as risk factors in cardiovascular and neurodegenerative diseases and increase in elderly with various comorbidities." (PMID 40149697, 2025). "Abnormal increases in the levels of TNF‐α and IL‐6 trigger a neuroinflammatory response, which is associated with various neurodegenerative diseases." (PMID 40458084, 2025). "TNF is a proinflammatory cytokine that has been implicated in various pathological conditions, including liver injury and neurodegenerative diseases." (PMID 40238193, 2025). "As TNF-α is a key pro-inflammatory cytokine produced by activated microglia and is implicated in the pathogenesis of various neurodegenerative diseases, including MS." (PMID 40471423, 2025). "This cluster also includes upregulated Pparg, a transcription factor that suppresses TNF expression and is neuroprotective, anti-inflammatory, and anti-mitochondrial dysfunction; the dysfunction of which is implicated in multiple neurodegenerative diseases." (PMID 41294802, 2025). "Neuroinflammation, a hallmark of neurodegenerative diseases, is driven by hyperactivated microglia and astrocytes that release pro‐inflammatory cytokines like IL‐1, TNF‐α, and IL‐6, exacerbating neuronal damage." (PMID 41018231, 2025). "During the inflammatory process, HMGB1 is secreted from necrotic cells and binds to many receptors, which triggers the release of many cytokines that cause inflammation and the development of neurodegenerative diseases, including IL-6, TNFα, and IL-1β." (PMID 41351800, 2025). "Although this study used serum samples, it was found that serum TNF-α can directly cause blood–brain barrier dysfunction by reducing extracellular resistance and cell polarity to induce or aggravate neurodegenerative diseases." (PMID 39295596, 2024). "Elevated levels of proinflammatory cytokines such as IFN‐γ, IL‐1β, IL‐6, IL‐18, and TNF‐α have been shown to induce tau hyperphosphorylation and neuronal loss in AD and other neurodegenerative diseases." (PMID 38923171, 2024). "Increasing levels of major proinflammatory cytokines, including TNF-α, IL-1β, and IL-6, are associated with several inflammatory-related neurodegenerative diseases." (PMID 37049819, 2023). "The cytokine TNF-α is a key controller of neuroinflammation associated with many neurodegenerative diseases, and overexpression of TNF-α in the hippocampus impairs memory and synaptic plasticity." (PMID 37081849, 2023). "Activated microglia can secrete large amounts of inflammatory cytokines, such as NO, IL-1β, TNF-α, etc., leading to a neuroinflammatory cascade that causes neuronal death and neurodegenerative diseases, including AD." (PMID 37895939, 2023). "The elevated TNF-α levels observed in neurodegenerative diseases have also been linked to the dysregulation of glutamate metabolism, a key excitatory neurotransmitter in the CNS." (PMID 37391534, 2023). "In neurodegenerative diseases, which are defined by neuronal degeneration and neuronal death in certain parts of the central nervous system (CNS), neuroinflammation by TNF-α and IL-6 is a crucial pathogenic mechanism underpinning neural death." (PMID 37871107, 2023). "TNF-α is an important pro-inflammatory cytokine that has widespread effects on the immune response, apoptosis and necrosis, and is associated with neurodegenerative diseases." (PMID 35379262, 2022). "Like sphingolipids, an up-regulated TNF-α expression has also been associated with the causation as well as the progression of several neurodegenerative diseases of the central nervous system (CNS)." (PMID 36060699, 2022).